BIRC6 (baculoviral IAP repeat containing 6)
Description:
Anti-apoptotic protein known as inhibitor of apoptosis (IAP) which can regulate cell death by controlling caspases and by acting as an E3 ubiquitin-protein ligase. Unlike most IAPs, does not contain a RING domain and it is not a RING-type E3 ligase. Instead acts as a dual E2/E3 enzyme that combines ubiquitin conjugating (E2) and ubiquitin ligase (E3) activities in a single polypeptide. Ubiquitination is mediated by a non-canonical E1 ubiquitin activating enzyme UBA6. Ubiquitinates CASP3, CASP7 and CASP9 and inhibits their caspase activity; also ubiquitinates their procaspases but to a weaker extent. Ubiquitinates pro-apoptotic factors DIABLO/SMAC and HTRA2. DIABLO/SMAC antagonizes the caspase inhibition activity of BIRC6 by competing for the same binding sites as the caspases. Ubiquitinates the autophagy protein MAP1LC3B; this activity is also inhibited by DIABLO/SMAC. Important regulator for the final stages of cytokinesis. Crucial for normal vesicle targeting to the site of abscission, but also for the integrity of the midbody and the midbody ring, and its striking ubiquitin modification.
Synonyms: BRUCE; APOLLON
Tractability: PROTAC: UniProt records ubiquitination sites on it; ubiquitination databases record sites on it; its protein half-life has been measured.
Gene: Protein-coding gene on chromosome 2 (32,357,023 to 32,619,571, forward strand). Ensembl gene ENSG00000115760.
Subcellular location: Golgi apparatus, trans-Golgi network membrane; Endosome; Cytoplasm, cytoskeleton, spindle pole; Cytoplasm, cytoskeleton, microtubule organizing center, centrosome; Midbody, Midbody ring
Subcellular location (Human Protein Atlas): Golgi apparatus; Vesicles; Mitotic spindle
Pathways (Reactome):
Disease: ALK mutants bind TKIs; Signaling by ALK fusions and activated point mutants
Gene Ontology:
Molecular function: cysteine-type endopeptidase inhibitor activity; protein binding; ubiquitin-protein transferase activity; ubiquitin conjugating enzyme activity
Biological process: negative regulation of apoptotic process; negative regulation of extrinsic apoptotic signaling pathway; regulation of cytokinesis; protein phosphorylation; protein ubiquitination; regulation of cell population proliferation; apoptotic process; placenta development
Cellular component: endosome; Golgi apparatus; membrane; microtubule organizing center; midbody; mitotic spindle; spindle pole; trans-Golgi network; cytosol; nucleus; centrosome; Flemming body
Genetic constraint (gnomAD): Loss-of-function variants: 71 observed, 405.55 expected, observed/expected ratio (o/e) 0.18, 90% interval 0.14 to 0.21. The upper end of that interval is the gene's LOEUF score, 0.21, which puts it in group 1 of 6, group 1 being the genes least tolerant of losing a copy. Missense variants: 4,824 observed, 5,308 expected, observed/expected ratio (o/e) 0.91, 90% interval 0.89 to 0.93. Synonymous variants: 2,067 observed, 1,911.1 expected, observed/expected ratio (o/e) 1.08, 90% interval 1.04 to 1.12.
Homologues: Orthologues: macaque BIRC6 (99% identical), chimpanzee BIRC6 (99% identical), pig BIRC6 (98% identical), rabbit BIRC6 (97% identical), rat Birc6 (96% identical), mouse Birc6 (96% identical), guinea pig BIRC6 (95% identical), tropical clawed frog birc6 (86% identical), zebrafish birc6 (81% identical), Drosophila melanogaster Bruce (33% identical), Caenorhabditis elegans ubc-17 (6% identical). Paralogues in human: NAIP (4% identical), BIRC2 (4% identical), BIRC3 (3% identical), NLRC4 (3% identical), XIAP (3% identical), BIRC7 (2% identical), BIRC5 (1% identical).
Diseases named in the same sentence as BIRC6 in open-access papers:
BIRC6 is named in the same sentence as 77 diseases in open-access papers, as found by Europe PMC text mining. Sharing a sentence is not in itself a finding about the gene and the disease. The quoted sentences say what the papers report.
breast carcinoma (12 papers, 2013 to 2025). "In the mFMC group, there was marked protein expression of BCL6, TXNRD3, CP and BIRC6, which have been linked with poor prognosis in human breast cancer." (PMID 38951817, 2024). "The mutations in BIRC6 were previously reported in several kinds of cancer including melanoma, glioma, breast cancer and pancreatic cancer." (PMID 23301059, 2013). "As we did in the in vitro analysis, we also explored the effects of BIRC6 silencing in in vivo assays of breast cancer." (PMID 41305480, 2025). "In order to evaluate the effects of BIRC6 silencing in lung and breast cancer cells, we designed one shRNA targeting BIRC6 mRNA." (PMID 41305480, 2025). "In breast cancer, BIRC6 has been suggested to play a key role in tumor homeostasis and in different stages of the metastatic cascade, including angiogenesis, migration and adhesion." (PMID 41305480, 2025). "BIRC6 has demonstrated overexpression in triple-negative human breast cancer cells and tissues, positively correlated with epidermal growth factor receptor (EGFR), and associated with poor patient survival time." (PMID 38951817, 2024). "The upregulation and overexpression of BIRC6 have been detected in various types of tumors, including gastric carcinoma, colorectal cancer, and primary breast cancer, compared with normal tissues." (PMID 38066801, 2023). "It has been reported that reduction of BIRC6 expression induces apoptosis (e.g., in breast cancer cells)." (PMID 23409057, 2013). "Additionally, we studied the effect of BIRC6 silencing over the apoptotic response in F3II breast cancer cells." (PMID 41305480, 2025). "In addition, we demonstrated that BIRC6 expression correlates with antiapoptotic and tumor progression-relevant markers in lung and breast cancer patients." (PMID 41305480, 2025). "Therefore, in this work, we present a new baculovirus-based gene therapy vector designed to silence the expression of the inhibitor of apoptosis BIRC6 and its preclinical validation on lung and breast cancer experimental models." (PMID 41305480, 2025). "In addition, BIRC6 is positively correlated with Ki-67 expression in various types of cancer, including breast cancer, hepatocellular carcinoma, and colorectal cancer." (PMID 38066801, 2023). "Recent evidence supports a widespread role for BIRC6 in conferring apoptosis resistance to cancer cells, as indicated by in vitro studies with cells from gliomas, lung cancers, cervical cancers, fibrosarcomas, osteosarcomas, breast cancers and colon cancers." (PMID 23409057, 2013). "We next correlated the expression of commonly shared identified genes; BIRC6, MAP3K2, USP4 and SMG1 with immune populations in different breast cancer subtypes." (PMID 38710724, 2024). "Only 0.5% of the total transcriptome correlated with the presence of Tregs and only four transcripts, BIRC6, MAP3K2, USP4 and SMG1, were commonly shared among the different breast cancer subtypes." (PMID 38710724, 2024). "Based upon further proteomics experiments, we found that EI001-induced apoptosis was associated with some potential ERK interactor involvements, such as HMGB1, BIRC6 and ATFM2 in breast cancer cells." (PMID 25742792, 2015).
prostate carcinoma (10 papers, 2013 to 2026). A carcinoma that arises from epithelial cells of the prostate gland. "Previous studies on prostate cancer revealed an association between BIRC6 expression and more advanced stages of the disease." (PMID 40510224, 2025). "Taken together, the data suggest that prostate cancer progression from benign to Gleason score 8 prostate cancers is associated with elevations in BIRC6 protein expression." (PMID 23409057, 2013). "The data suggest that development of castration-resistant prostate cancer is associated with elevations in BIRC6 protein expression." (PMID 23409057, 2013). "Another study in a patient-derived xenograft model of castration-resistant prostate cancer also demonstrated that high BIRC6 protein levels were associated with resistance to the androgen receptor inhibitor enzalutamide and that targeting BIRC6 inhibited cancer growth both in vitro and in vivo." (PMID 40768895, 2025). "Furthermore, BIRC6 overexpression has been associated with worse overall survival and shorter disease-free survival in colorectal cancer, prostate cancer, and childhood AML and acute lymphoblastic leukemia (ALL)." (PMID 40510224, 2025). "However, previous studies reported a significant association between the BIRC6 level of patients and healthy subjects, including colorectal cancers, lung, and prostate cancer." (PMID 36033570, 2022). "We recently showed elevated expression of BIRC6 in prostate cancer cell lines and clinical specimens, and found that increased BIRC6 expression was associated with Gleason score 6-8 prostate cancers and CRPC, suggesting a role for BIRC6 in prostate cancer progression and castration resistance." (PMID 25071009, 2014). "Taken together, these data demonstrate that loss of BIRC6 expression in LNCaP prostate cancer cells leads to inhibition of autophagy and that BIRC6 may be a positive regulator of autophagy." (PMID 23409057, 2013). "The anti-apoptotic role of BIRC6 could likely be involved in the development of castration-resistant prostate cancer and underlie therapy resistance in this advanced form of the disease." (PMID 23409057, 2013). "Identification of the significant role of BIRC6 in cancer progression and response to treatment has resulted in the suggestion of BIRC6 as a novel target for anticancer therapy in different cancers, such as prostate cancer." (PMID 40510224, 2025). "One of the proteins which have currently been used as a predictor of different cancer prognoses such as acute leukemia, ovarian epithelial cell carcinoma, prostate cancer, and other cancer types was BIRC6." (PMID 36033570, 2022). "In the present study, we showed a correlation between elevated BIRC6 expression in clinical prostate cancer specimens and poor patient prognostic factors, as well as co-upregulation of certain IAP members." (PMID 25071009, 2014). "In the present study, we established, using a larger cohort of clinical prostate cancer samples, a correlation between elevated BIRC6 expression and advanced prostate cancer - evidence supporting a role for BIRC6 in the malignant progression of the disease." (PMID 25071009, 2014). "BIRC6 has been found to be overexpressed in various carcinomas, such as prostate cancer, melanoma, and non-small-cell lung cancer." (PMID 25254241, 2014). "This is consistent with our previous study demonstrating that BIRC6 is upregulated in Gleason 6-8 prostate cancers and CRPC." (PMID 25071009, 2014). "This study shows that BIRC6-based dual IAP-targeting ASOs represent potential novel therapeutic agents against advanced prostate cancer." (PMID 25071009, 2014). "As BIRC2 (cIAP1), BIRC4 (XIAP) and BIRC5 (survivin) tended to be co-upregulated in prostate cancer in addition to BIRC6, simultaneous targeting of BIRC6 plus one of these IAP members was more likely to give superior anti-cancer effects." (PMID 25071009, 2014).
prostate carcinoma (continued). "In conclusion, the present study indicates for the first time that the BIRC6 gene and its product are potentially valuable targets for treatment of prostate cancers showing elevated BIRC6 expression." (PMID 23409057, 2013). "Elevated BIRC6 protein expression was found in prostate cancer cell lines and clinical specimens as distinct from their benign counterparts." (PMID 23409057, 2013). "Taken together, the results suggest that BIRC6 represents a novel therapeutic target for treatment of refractory prostate cancer." (PMID 23409057, 2013). "Gleason grade 5 tissues generally expressed lower levels of BIRC6 staining relative to the other prostate cancer tissues, similar to benign tissues." (PMID 23409057, 2013). "Western blotting revealed strong BIRC6 protein expression in all prostate cancer cell lines examined." (PMID 23409057, 2013). "Specific reduction of BIRC6 expression by siRNAs led to a marked inhibition of prostate cancer cell viability, which notably was coupled to a marked increase in Annexin-V positive cells and the expression of apoptosis markers." (PMID 23409057, 2013). "In the present study, analysis of human prostate cancer cell lines and clinical specimens showed marked elevations in BIRC6 expression by the malignant cells/tissues as distinct from their benign counterparts." (PMID 23409057, 2013). "The increase in BIRC6 expression in Gleason 6–8 clinical prostate cancers, including castration-resistant cancers, suggests an important role for this protein in the development and progression of the disease." (PMID 23409057, 2013). "The expression of BIRC6 over the course of prostate cancer progression reached peak levels in Gleason score 7 cancers but had levels in Gleason score 9–10 prostate cancers that were similar to those of benign tissues." (PMID 23409057, 2013). "We used the LNCaP cell line to study the effect of reducing BIRC6 expression on prostate cancer cell viability." (PMID 23409057, 2013). "The data suggest a role for BIRC6 in prostate cancer progression and treatment resistance, and indicate for the first time that the BIRC6 gene and its product are potentially valuable targets for treatment of prostate cancers." (PMID 23409057, 2013). "Some studies have shown that BIRC6 expression could be related to the grade of tumors, for instance, in non-small-cell lung carcinoma and prostate cancer." (PMID 38066801, 2023). "Here we report the first therapeutic agents developed to target BIRC6 in prostate cancers." (PMID 25071009, 2014). "Taken together, the data indicate that BIRC6, like survivin, may play a role in prostate cancer progression." (PMID 25071009, 2014). "In conclusion, the present study indicates that BIRC6-based dual-IAP targeting ASOs may represent novel therapeutic agents against advanced prostate cancer." (PMID 25071009, 2014). "As such, BIRC6 represents an attractive therapeutic target for prostate cancer." (PMID 25071009, 2014). "Only 6w2 and 6w5-1 markedly reduced BIRC6 protein levels in prostate cancer cells." (PMID 25071009, 2014). "We examined whether various clinical parameters of prostate cancer, i.e. clinical T stage, PSA recurrence, lymph node metastasis and prostatic capsule invasion, were associated with changes in BIRC6 protein expression." (PMID 25071009, 2014). "In view of the pro-survival function of BIRC6 in prostate cancer cells and in other systems, elevations in the expression of BIRC6 are expected to provide a cytoprotective advantage to prostate cancer cells and promote prostate cancer development and progression." (PMID 23409057, 2013). "Also, the low intensity of expression observed in Gleason score 9–10 prostate cancer tissues was reflective of the large proportion of typically weak BIRC6-expressing Gleason grade 5 cancers found in this group." (PMID 23409057, 2013).
prostate carcinoma (continued). "It is therefore conceivable that the elevated expression of BIRC6 observed in castration-resistant prostate cancers may be responsible for the treatment resistance of refractory disease." (PMID 23409057, 2013). "Targeting BIRC6 as an inhibitor of apoptosis and potential enhancer of autophagy may be useful for sensitizing prostate cancer cells to anti-cancer therapies." (PMID 23409057, 2013). "Furthermore, siRNA-induced knockdown of BIRC6 led to a marked reduction in cell proliferation of LNCaP prostate cancer cells." (PMID 23409057, 2013). "Positive cytoplasmic staining for BIRC6 was, generally, low in benign epithelium, substantially more intense in well differentiated Gleason grade 3 and strongest in poorly differentiated Gleason grade 4 prostate cancer tissues." (PMID 23409057, 2013). "The effect of BIRC6 reduction was also studied in PC-3 prostate cancer cells." (PMID 23409057, 2013). "BIRC6 was found to be functionally critical for the survival of prostate cancer cells." (PMID 23409057, 2013). "Elevated BIRC6 expression also correlated positively with poor prognostic factors such as PSA recurrence, lymph node metastasis and prostatic capsule invasion (p = 0.0571, 0.0286 and 0.0246, respectively, Chi square test for trend), indicative of its association with more advanced prostate cancer." (PMID 25071009, 2014). "With increasing evidence that autophagy may serve as a survival mechanism of cells in response to stress, including anti-cancer therapeutics, BIRC6 may be a suitable target for inhibition of autophagy-mediated cell survival and for treatment resistance in prostate cancer cells." (PMID 23409057, 2013). "In contrast to earlier reports, our study established that the BIRC6 protein is markedly expressed by a variety of conventional malignant prostate cell lines as distinct from benign prostate cell lines, indicating that BIRC6 could have a significant role in prostate cancer." (PMID 23409057, 2013). "In prostate cancer, MALAT1 facilitates tumor cell proliferation, migration, and invasion by modulating signaling pathways, including the miR‐140/BIRC6 axis, thus contributing to tumor progression." (PMID 41584724, 2026). "We designed antisense oligonucleotides (ASOs) that simultaneously target BIRC6 and an additional IAP to achieve maximal anti-tumor activity, as elevated expression in prostate cancer has also been reported for other IAPs such as survivin and cIAP1." (PMID 25071009, 2014). "In the present study, we established that elevated expression of BIRC6 protein, a less investigated IAP family member, is correlated with poor prognosis of prostate cancer patients." (PMID 25071009, 2014). "While the large majority of prostate cancer tissues exhibited BIRC6 protein elevations, not all stages of the disease expressed elevated levels of the protein." (PMID 23409057, 2013). "On the other hand, the levels of BIRC6 protein were elevated in castration-resistant Gleason 8–10 prostate cancers compared to non-castrated counterparts." (PMID 23409057, 2013). "The main objective of the present study was to investigate whether BIRC6 plays a role in prostate cancer and could be useful as a novel therapeutic target." (PMID 23409057, 2013). "A role for BIRC6 in prostate cancer, however, has not been reported." (PMID 23409057, 2013). "While BIRC6 expression may not be required in advanced stage prostate cancer, the resurge of BIRC6 in CRPC may suggest that cellular stress, e.g. castration, may trigger the overexpression of cytoprotective BIRC6." (PMID 23409057, 2013).
acute myeloid leukemia (9 papers, 2012 to 2025). Acute myeloid leukemia (AML) is a group of neoplasms arising from precursor cells committed to the myeloid cell-line differentiation. "BIRC6 overexpression was associated with unfavorable prognosis in childhood de novo acute myeloid leukemia." (PMID 25933218, 2015). "Overexpression of the IAP BIRC6 is associated with unfavorable clinical features and negatively impacts relapse-free survival in childhood acute myeloid leukemia (AML)." (PMID 23211188, 2012). "Birc6 is a regulator of apoptosis and has been described as being deregulated in acute myeloid leukemia." (PMID 30388136, 2018). "BIRC6 expression in clinical cancer samples has been observed for colorectal cancer and childhood de novo acute myeloid leukemia (AML)." (PMID 23409057, 2013). "Furthermore, lower BIRC6 levels have been confirmed in some types of cancers, such as acute myeloid leukemia (AML)." (PMID 40510224, 2025). "The elevated BIRC6 expression in the basal or peripheral cells of the specimens, especially the OSCC samples, agreed with the findings of previous studies in gastric carcinoma and childhood acute myeloid leukemia." (PMID 38066801, 2023).